ADAMTS13 (ADAM metallopeptidase with thrombospondin type 1 motif 13)
Diseases named in the same sentence as ADAMTS13 in open-access papers (continued):
Sharing a sentence is not in itself a finding about the gene and the disease.
Stroke (continued). "ADAMTS13 is a well-described cleaving protease of von Willebrand factor (vWF), a key player in thrombus formation and has been suggested a new therapeutic agent for promoting stroke recovery." (PMID 33930055, 2021). "Furthermore, in animal models of stroke, ADAMTS13 not only affects infarct volume, but also controls neuroinflammation and recovery, along with the maintenance of cerebrovascular integrity." (PMID 32731558, 2020). "Moreover, recent studies have confirmed the effect of the ADAMTS13-VWF axis on BBB permeability in models of stroke, traumatic brain injury, and cerebral malaria." (PMID 32075652, 2020). "It has been reported that the previously identified, dose-dependent activity of wild-type ADAMTS13 in murine models of stroke could be further improved by conformational preactivation." (PMID 31379722, 2019). "These indicate that low levels of ADAMTS13 are an independent predictor of stroke." (PMID 31379722, 2019). "Recently, ADAMTS13 has been reported to be closely related to stroke." (PMID 31379722, 2019). "It has been concluded that miR-525-5p might negatively regulate the expression of ADAMTS13 after stroke." (PMID 31379722, 2019). "Mice lacking ADAMTS13 suffered from severely worsened ischemic brain damage following experimental stroke, while intravenous administration of recombinant ADAMTS13 prior to reperfusion reduced infarct size and improved functional outcome after focal cerebral ischemia." (PMID 31736950, 2019). "Therefore, complete deficiency in ADAMTS13 seems to result in a prothrombotic state, which is an important risk factor for TTP or stroke, but it is insufficient to cause TTP or stroke by itself." (PMID 31379722, 2019). "We hypothesized that the previously identified, dose‐dependent activity of wild‐type (WT) ADAMTS‐13 in murine models of stroke may be further improved by conformational preactivation." (PMID 30152919, 2018). "The ability of GoF ADAMTS‐13 to reduce the size of preformed, stable platelet aggregates in vitro suggested that its protective effect in experimental stroke may be sustained even when administration is delayed." (PMID 30152919, 2018). "Furthermore, when assessing the VWF:ADAMTS13 ratios, an even greater difference was revealed between stroke patients (2.7 ± 1.9), HV (1.1 ± 0.5) and CCD patients (1.7 ± 0.7)." (PMID 28591212, 2017). "As already mentioned, because of the case–control study design of this study, it is not possible to assign causality of ADAMTS13 levels to the occurrence of stroke." (PMID 28591212, 2017). "Furthermore, it would be of particular interest to show whether there are etiological differences in ADAMTS-13 activity also in the acute phase following stroke." (PMID 36703637, 2022). "Moreover, lower ADAMTS-13 activity was also implicated in the risk for deep vein thrombosis (DVT), which may be of interest in the mechanisms of paradoxical embolism in stroke patients with PFO." (PMID 36703637, 2022). "The difference between these research results may be explained by differences in the study inclusion criteria because infection, excessive alcohol consumption, pregnancy, drug/medication use, injury, food poisoning, and others can influence the impact of ADAMTS13 on stroke." (PMID 31379722, 2019). "At least in preclinical animal research, targeting VWF via anti-VWF-GPIbα strategies or recombinant ADAMTS13 did not increase the risk of intracranial hemorrhaging in murine stroke models, even when combined with tissue-plasminogen activator or when treatment was delayed." (PMID 31921147, 2019). "The fact that GoF ADAMTS‐13 was effective at lower doses than WT ADAMTS‐13 most likely reflects the enhanced activity of the preactivated ADAMTS‐13 variant, which could become useful in the setting of stroke." (PMID 30152919, 2018). "We show that SARS‐CoV2 infections drive a VWF/ADAMTS13 axis imbalance, inducing an increase in tPA while decreasing FIX, MMP‐2, and sICAM‐1 post‐stroke." (PMID 39972966, 2025).
Stroke (continued). "This study provides the first data on ADAMTS-13 levels in patients with ESUS and particularly in stroke patients with PFO." (PMID 36703637, 2022). "Of note, the AUCs for GDF-15, D-dimer, ADAMTS13, CCL2/MCP-1, IL-4, CC4b, IL-7, ferritin, SAA, CCL1/I-309 and IL-10 were ≥0.75 in indicating stroke amongst children with TBM." (PMID 33930055, 2021). "In patients with cardiovascular disease, including CAD and stroke, VWF and ADAMTS13 are both predictors of future CV events." (PMID 28634421, 2017). "Nonetheless, given the absence of a clear alternative attributable stroke mechanism, low ADAMTS13 activity, and high ADAMTS13 Bethesda inhibitor titer, TTP was suspected as the etiology of her ischemic strokes." (PMID 40109809, 2025). "Plasma levels of ADAMTS13 were within the normal range for the non‐stroke control cohort and SARS‐CoV2 negative IS cohort, while they were significantly decreased in the SARS‐CoV2 positive IS cohort." (PMID 39972966, 2025). "Overall, our results indicate that ADAMTS-13 is associated with vascular risk factors and not with the risk of paradoxical embolism in the young collective of patients with PFO-associated stroke." (PMID 36703637, 2022). "Strengths of our study include the utilization of two prospectively enrolled and comprehensively characterized stroke cohorts with biomarker sampling in the long-term course, which excludes stroke-induced effects on ADAMTS-13 levels." (PMID 36703637, 2022). "Stroke after recovery from acute TTP occurred in 0% (0 of 22) of patients with normal remission ADAMTS13 activity (> 70%) and in 27.6% (8 of 29) of patients with low ADAMTS13 activity (≤ 70%)." (PMID 33586004, 2021). "In a prospective cohort study, the activity of plasma ADAMTS13 was tested in 5,941 volunteers who were over 55 years old without a history of stroke or transient ischemic attack." (PMID 31379722, 2019). "Complete lack of ADAMTS13 in mice does not necessarily result in stroke, but does lead to a prothrombotic state." (PMID 31379722, 2019). "Given the potential role of ADAMTS13 and VWF in stroke progression and severity, we correlated the levels of ADAMTS13 and the VWF:ADAMTS13 ratios in AIS and TIA patients on day 0 with key demographic and clinical parameters by univariate and multivariate analysis." (PMID 28591212, 2017). "The time point of blood withdrawal for the stroke patients (days 0, 1 and 3) did not influence ADAMTS13 levels (p = 0.630) or the VWF:ADAMTS13 ratio (p = 0.990)." (PMID 28591212, 2017). "Overall, our study has highlighted that the thromboinflammatory response post‐stroke is affected by the preceding SARS‐CoV2 infection by enhancing the VWF/ADAMTS13 axis imbalance and does not elevate to the same magnitude the protein levels of MMP‐2, sICAM‐1, and FIX." (PMID 39972966, 2025). "Congenital TTP patients receiving treatment with regular prophylactic donor plasma infusions to replace ADAMTS13 report symptomatic relief with commencement of prophylaxis and also have a significantly reduced incidence of stroke (2% vs. 17%) compared to those not receiving prophylaxis." (PMID 39274365, 2024). "Additionally, patients with imaging-confirmed stroke showed higher plasma concentrations of anti-ADAMTS13 IgG than those without stroke." (PMID 33458563, 2021). "However, an animal model study showed that a lack of ADAMTS13 in mice led to a pre-thrombotic state instead of stroke." (PMID 34276770, 2021). "As GoF ADAMTS‐13 shows an increased ability to dissolve VWF/platelet‐rich aggregates in vitro, we hypothesized that it may exert a more pronounced protective effect than WT ADAMTS‐13 in an experimental model of stroke." (PMID 30152919, 2018). "We then compared the plasma levels of D-dimer, OPN, OPG, vWF, and ADAMTS13 in LVO and non-LVO patients; the plasma levels of GFAP were compared in hemorrhagic vs. ischemic stroke and non-stroke patients." (PMID 34206615, 2021).
thrombosis (48 papers, 2014 to 2026). "In the absence or reduction of ADAMTS13 activity, ultra-large von Willebrand factor strings remain anchored at the endothelium and can recruit flowing platelets and causing uncontrolled thrombosis in terminal arterioles and capillaries." (PMID 41160661, 2025). "Factor V Leiden increases the risk for venous thrombosis four- to eightfold when it occurs in a heterozygote state, while a mutation in ADAMTS13 is likely pathogenic for familial TTP." (PMID 40650005, 2025). "This expands our understanding of the impact of severe ADAMTS13 deficiency associated with non‐overt microvascular thrombosis, escalating our understanding of disease pathophysiology." (PMID 35845267, 2021). "In the last years, the role of the ADAMTS13 gene as a genetic risk factor for both arterial and venous thrombosis has been explored." (PMID 34662354, 2021). "In our patient cohort, VWF and the ADAMTS‐13/VWF were associated with occurrence of cancer‐associated thrombosis." (PMID 31294335, 2019). "Besides TTP, an imbalance in the VWF:ADAMTS-13 axis was linked to ischemic stroke and coronary occlusion and to increased risk for arterial and deep-vein thrombosis." (PMID 38399555, 2024). "Furthermore, we found that elevated levels of factor VIII and VWF and decreased levels of ADAMTS-13 were associated with an increased incidence of thrombosis in PCR positive patients." (PMID 35482749, 2022). "Not only ADAMTS-13 variants but also VWF and FVIII variants can be responsible for plasma levels of these molecules and thrombosis risk." (PMID 40557182, 2025). "ADAMTS13-resistant von Willebrand factor–platelet tangles are the nidus for venous thrombosis development." (PMID 39908367, 2025). "VWF not only plays a role in arterial and venous thrombosis, but in atherosclerosis, and thrombosis accompanying malaria, sepsis, and sickle cell anemia, where ADAMTS13 activity is at or near normal levels." (PMID 39445200, 2024). "The ADAMTS13/VWF ratio is considered a sensitive index to evaluate blood flow in liver-related splanchnic vein thrombosis." (PMID 38672756, 2024). "Higher levels of fibrinogen and vWF can lead to intravascular thrombosis, vascular damage, and thrombotic complications, whereas lower levels of ADAMTS13 result in decreased cleavage of large prothrombotic vWF multimers." (PMID 34559294, 2022). "The patients that developed thrombosis had elevated levels of established risk factors for thrombosis such as higher VWF and FVIII levels and lower ADAMTS-13 levels." (PMID 35482749, 2022). "ADAMTS-13 levels were significantly lower in PCR positive patients with thrombosis (597±27 ng/mL vs. 691±27 ng/mL, p<0.001)." (PMID 35482749, 2022). "Centralized ADAMTS13 activity testing was performed at the Milan Hemophilia and Thrombosis Center within 24 h." (PMID 35739601, 2022). "Increased levels of disintegrins and metalloproteases with a thrombospondin type 1 motif, member 13 (ADAMTS-13), and VWF are causative for cardiovascular events in SLE patients, as well as venous thrombosis." (PMID 34461924, 2021). "Between January 2002 and March 2018, 252 patients were referred to the Angelo Bianchi Bonomi Hemophilia and Thrombosis Center for ADAMTS13 testing for a first episode of iTTP." (PMID 33096882, 2020). "In the framework of the ongoing prospective Cancer and Thrombosis Study (CATS) ADAMTS‐13 activity and VWF antigen levels were investigated in cancer patients." (PMID 31294335, 2019). "It points to their importance in hemostasis, bleeding disorders, and the developing field of therapeutic application of ADAMTS‐13 as an antithrombotic agent in obstructive microvascular thrombosis and in cardiovascular disease." (PMID 29108103, 2018). "The limited proteolytic activity of WT ADAMTS‐13 in in vitro models of arterial thrombosis suggests an in vivo requirement for conformational activation." (PMID 30152919, 2018).
thrombosis (continued). "Although the effects imposed by surgery were described, the levels of VWF and ADAMTS13 may change more dramatically or in an unexpected manner in overt thrombosis." (PMID 36362664, 2022). "VWF antigen/ADAMTS13 ratio has a significant prognostic power at different time points after heart attacks concomitant with higher chances of adverse outcomes in clinical practise, like heart failure and thrombosis." (PMID 32095288, 2020). "The vWF:Ag/ADAMTS-13 ratio increased by 57.7% before thrombosis." (PMID 33292287, 2020). "Whether reduced ADAMTS13 activity would play a role in the endothelial dysfunction and risk of thrombosis associated with B. lanceolatus envenoming have not been studied." (PMID 41160661, 2025). "Therefore, based on the previous evidence on the role of ADAMTS-13 in venous thrombosis, we hypothesized that patients with a higher probability for a pathogenic PFO may reveal lower ADAMTS-13 levels." (PMID 36703637, 2022). "TTP, typically characterized by a deficit in the activity (< 10%) of ADAMTS13 leading to the accumulation of ultra‐large VWF multimers platelet aggregation, endothelial damage, and microvascular thrombosis and ischemia, shows an incidence of < 1/100 000/year." (PMID 40206570, 2025). "Dysregulation of the ADAMTS13-VWF axis can result in hemostatic abnormalities, manifesting as bleeding or thrombosis." (PMID 41311061, 2025). "The cytokine-mediated suppression of ADAMTS13 activity results in VWF imbalances, which lead to microvascular thrombosis and unfavorable clinical outcomes, particularly in patients with disseminated intravascular coagulation." (PMID 40725629, 2025). "In contrast to ADAMTS-13, HMGB1 has been shown in an animal model of deep vein thrombosis to induce pro-thrombotic neutrophil extracellular trap formation and in vivo/in vitro platelet aggregation." (PMID 37863934, 2023). "Under oscillatory flow patterns in the presence of ADAMTS13, the VWF-platelet tangles and knots that formed on the endothelial surface bear resemblance to the pattern of platelet accumulation during the initiation of venous thrombosis in the stenosis model." (PMID 39908367, 2025). "The imbalance of the ADAMTS13-VWF axis due to chronic hyperglycemia may lead to thrombotic vascular disease in diabetic patients, while intrarenal thrombosis aggravates diabetic nephropathy." (PMID 39830349, 2024). "Last, we were unable to investigate the relationship between DVT and other endothelial biomarkers, such as tissue factor activity, prothrombin fragments, the level of coagulation factor VIII, the dynamics of D-dimer, hereditary thrombosis risk factors or the effect of ADAMTS-13." (PMID 33292287, 2020). "ADAMTS-13 activity was higher in vascular BD with thrombosis than non-vascular subgroup." (PMID 40557182, 2025). "In addition, the reduced levels of ADAMTS-13, which is responsible for cleaving VWF into smaller and less active molecules, in the thrombosis group supports the implication of VWF and ADAMTS-13 in the pathogenesis of the typical SARS-CoV-2 prothrombotic phenotype." (PMID 35482749, 2022). "Fourth, although we included many outpatients with LC, this study excluded those with the presence of occult thrombosis-provoking factors, those in whom CECT could not be performed, and those in whom ADAMTS13:AC and VWF:Ag could be affected." (PMID 38473925, 2024).
ischemic stroke (42 papers, 2011 to 2026). A stroke disorder caused by obstruction of blood flow to the brain, due to thrombotic (local blood clot formation) or embolic (due to a blood clot or other material traveling from another site) event. "Those with an ADAMTS13 activity in the lowest quartile had a significantly higher risk of ischemic stroke than those in the highest quartile (absolute risk, 7.3% vs. 3.8% respectively; hazard ratio, 1.65; 95% confidence interval [CI], 1.16–2.32)." (PMID 39274365, 2024). "The meta-analysis based on published results confirmed a significant association of ADAMTS-13 levels with ischemic stroke (relative risk (RR), 2.72; 95% CI, 1.52 to 4.85, for low versus high ADAMTS-13 levels)." (PMID 39199353, 2024). "With ischaemic stroke being a major cause of morbidity and mortality worldwide, and available treatments options being sub-optimal, there is huge potential for using ADAMTS13 as a novel therapeutic target in these patients." (PMID 39274365, 2024). "Due to its antithrombotic properties, low ADAMTS13 activity seems to be a risk factor for the development of ischemic stroke and myocardial infarction." (PMID 36574434, 2022). "The MR–Egger regression showed that there was a pleiotropic effect influencing the verification of the causal relationship between ADAMTS13 level and ischemic stroke (p < 0.05)." (PMID 34276770, 2021). "The contribution of ADAMTS13 to cerebral vascular integrity is supported by finding low ADAMTS13 activity associated with increased risk of dementia, ischemic stroke, and subarachnoid hemorrhage." (PMID 33178104, 2020). "Recent case-control studies also demonstrated that the higher plasma vWF or lower ADAMTS13 levels were closely associated with the risk of MI, ischaemic stroke." (PMID 32039706, 2020). "Very low (less than 10%) ADAMTS-13 activity causes the disease TTP and moderately low ADAMTS-13 activity is associated with ischaemic stroke, which is also a feature of TTP." (PMID 33352066, 2020). "It was found that individuals with lower ADAMTS13 activities had a higher risk of ischemic stroke than those with normal ADAMTS13 activities." (PMID 31379722, 2019). "The importance of decreased ADAMTS13 as an important risk factor for ischemic stroke in humans has promoted experimental trials in acute stroke models." (PMID 31379722, 2019). "In contrast, low ADAMTS13 was associated with increased risk of dementia throughout follow-up (hazard ratio per SD decrease– 1.16 [1.06–1.28]), which alike for ischaemic stroke, was modified by the presence of diabetes (P-interaction = 0.003)." (PMID 29615758, 2018). "Due to the case-control design of our study we cannot draw conclusions about causality of low ADAMTS13 levels and the occurrence of ischemic stroke." (PMID 28591212, 2017). "Endothelial dysfunction may also play a role in the mechanism of LVNC thromboembolic complications, since low ADAMTS13 levels were associated with an increased risk of arterial thrombosis and ischemic stroke." (PMID 37297827, 2023). "In this study, we, therefore, aimed to investigate whether ADAMTS-13 may be a circulating biomarker that supports the identification of the underlying mechanism of ischemic stroke." (PMID 36703637, 2022). "ADAMTS13 has previously been linked toatrial fibrillation and ischemic stroke, and our findings suggest that the1342G-allele may be of significance." (PMID 36474435, 2022). "Furthermore, ADAMTS-13 was repeatedly implicated in the pathophysiology of ischemic stroke and was shown to be associated with response to reperfusion therapies of acute cerebral ischemia." (PMID 36703637, 2022). "Furthermore, in a pediatric cohort study, researchers regarded reduced ADAMTS13 activity as a risk factor for pediatric ischemic stroke." (PMID 34276770, 2021). "Most studies have linked ADAMTS13 levels to the risk of ischemic stroke in the general population." (PMID 34276770, 2021). "They found that low ADAMTS13 activity is an independent risk factor of ischemic stroke." (PMID 34819564, 2021).